MMP9 (matrix metallopeptidase 9)
Diseases named in the same sentence as MMP9 in open-access papers (continued):
Sharing a sentence is not in itself a finding about the gene and the disease.
tumor (continued). "This may suggest that high sera MMP-9 represents increased intrinsic tumor activity, which manifests, among other factors, with increased MMP-9 secretion." (PMID 41573658, 2025). "MMP1, MMP3, and MMP9 have also been shown to play critical roles in tumor metastasis." (PMID 40486048, 2025). "On one hand, with MMP-9, cathepsin G, and neutrophil elastase (NE), NETs could induce tumors via promoting tumor distant site spread, shielding immune cell infiltration, killing immune cells, and provoking tumor angiogenesis and cancer-associated thrombosis." (PMID 40868150, 2025). "In addition to affecting tumor cell migration by directly acting on MMP-9, indirect mechanisms have been identified." (PMID 41181710, 2025). "Additionally, quercetin suppresses tumor invasion in MCF-7 cells by inhibiting matrix metalloproteinase-9 (MMP-9) activity by downregulating the PKCδ/ERK/AP-1 signaling pathway." (PMID 40438489, 2025). "Among them, MMP2 and MMP9 play important roles in promoting tumor cell metastasis." (PMID 40520902, 2025). "Moreover, numerous studies have demonstrated that MMP9 is primarily involved in the migration and invasion of tumor cells." (PMID 40801260, 2025). "In addition, HSP can inhibit certain tumor-related growth factors, which will prevent metastasis, inhibit MMP-9 production, and arrest the cell cycle in the Sub G1 phase." (PMID 40427522, 2025). "The overexpression of miR-124, which functions as a tumor suppressor in BC, markedly inhibits the expression of angiogenesis markers including VEGF, MMP-2, and MMP-9, thereby suppressing the migration, invasion, and angiogenesis of BC cells in vitro, as well as tumor growth in vivo." (PMID 39981244, 2025). "Vimentin and N‐cadherin are key markers of the epithelial–mesenchymal transition (EMT), a process that enhances cell motility and invasiveness, while MMP2 and MMP9 are matrix metalloproteinases involved in the degradation of the extracellular matrix, facilitating tumour invasion and metastasis." (PMID 40794013, 2025). "TAMs release TGF-β, IL-1β, and IL-6, which increase MMP-9 in tumour cells." (PMID 40361472, 2025). "We found that the levels of combination signatures CM-2 (HYAL-1 + N-Cadh) and CM-6 (HYAL-1 + N-Cadh + HAS-2 + SNAI1 + Slug + MMP-9) were elevated 5–8-fold in tumor specimens from patients who had or developed metastasis during follow-up compared to those who did not (p < 0.0001)." (PMID 40149256, 2025). "Similarly, the application of GM6001 during the induction phase partially reduced the induction of MMP-9 in responder tumor cells, scratch closure, upper CAM tumor weight and angiogenesis." (PMID 40155451, 2025). "Notably, co-expression of MMP9 with GNL staining was observed in overlapping tumor regions in all MMP9 positive cases, encompassing both cellular and secretory compartments." (PMID 41041068, 2025). "Notably, standard GB treatments such as radiation and temozolomide (TMZ) further upregulate MMP-9 expression, potentially exacerbating tumor aggressiveness." (PMID 41154699, 2025). "Additionally, migration assays and gelatin zymography demonstrated that the analogs, unlike vemurafenib, significantly inhibited matrix metalloproteinases MMP-2 and MMP-9, key enzymes involved in tumor invasion and metastasis." (PMID 40872552, 2025). "Additionally, HIF-1α can also promote tumor proliferation and invasion by modulating the expression of the proto-oncogene c-myc and the matrix metalloproteinase MMP9." (PMID 41154694, 2025). "In cancer pathology, MMP-9 induces the invasion of cancer cells, promoting tumor development." (PMID 40869267, 2025). "Since MMPi was equally effective as proteinase K in blocking EV-mediated TGF-β signaling, MMP9 (or another MMP) must play an important role in facilitating TGF-β signaling by tumor cell-derived EVs, most logically, by activating the predominant latent TGF-β form." (PMID 39910665, 2025).
tumor (continued). "In addition to E-cadherin, the activation of the snail family transcriptional repressor 2 (SNAI2) and the heightened levels of matrix metalloproteinase 9 (MMP9) are also vital elements involved in EMT throughout tumor progression." (PMID 40108613, 2025). "Since NET formation was a prominent feature of “responder” supernatants in our system, we tested whether NE and MMP-9, two main components of NETs, could drive the observed tumor cell changes." (PMID 40155451, 2025). "Cancer cells may infiltrate and invade surrounding tissue through MMP-9–mediated degradation of the basement membrane of newly formed blood vessels, promoting tumor growth and angiogenesis through VEGF activation." (PMID 40729026, 2025). "It has been proposed that HSP90 activates CSC mechanisms which upregulate the expression of MMP-2 and MMP-9 and that interaction with secreted MMPs induces local degradation of the extracellular matrix and enhances tumor cells migration, especially those with the CSC phenotype." (PMID 41369386, 2025). "Furthermore, we identified multiple, additional hallmarks of CACs harboring Mir34a-deficient myeloid cells, such as increased expression of Mmp9 in neutrophils and elevated expression of Zeb2 in an inflammatory subtype of CAC tumor cells." (PMID 39425000, 2025). "For potential testing in in vivo studies, co-occurrence of the antigen on the tumor and sufficient concentration of MMP-9 in the TME would be required, as well as further linker design for endosomal release while avoiding premature proteolytic cleavage of the TAA-binding antibody fragment in serum." (PMID 39895690, 2025). "Following treatment with RLN2-secreting CAR-T cells, type IV collagen expression in the tumor was significantly reduced by RLN2-induced MMP-9 and MMP-7 expression, potentially facilitating easier contact between the extravasated CAR-T and cancer cells after traversing the interstitial stroma." (PMID 40666525, 2025). "Additionally, it inhibits proteasome activity, DNA methyltransferases, and matrix metalloproteinases (MMP-2 and MMP-9), thereby suppressing tumor progression, invasion, and the epigenetic silencing of tumor suppressor genes." (PMID 40871008, 2025). "For example, lung endothelial cells, in response to VEGF secreted from experimental or human tumors, secrete enhanced levels of matrix metalloproteinase 9 (MMP-9), even before tumor cells spread, and render the lung tissue more receptive to tumor cell invasion." (PMID 40370456, 2025). "After expression, MMP-9 can degrade and disrupt the extracellular matrix on the tumor surface, enabling tumor cells to infiltrate and grow into surrounding tissues along the missing basement membrane, ultimately leading to the invasion and metastasis of OS cells." (PMID 41296391, 2025). "Moreover, MMP9 is important for degrading extracellular matrix components, facilitating tumor invasion and metastasis." (PMID 39858010, 2025). "Given the well‐characterised roles of MMP2 and MMP9 in extracellular matrix degradation and metastatic dissemination, their suppression suggests a mechanistic link between PTGER4 deficiency and impaired tumour invasiveness." (PMID 41284374, 2025). "TGF-β assists MMP-2 and MMP-9 promote tumor growth and metastasis." (PMID 40563423, 2025). "Moreover, MMP-2, a collagenase IV is involved in tissue remodeling and tumor invasion by degrading extracellular matrix components, MMP-9 is involved in developing malignancies and enhances tumor angiogenesis, progression, invasion, and metastasis." (PMID 40740599, 2025). "THBS1 also promotes tumor metastasis in post-dormancy stages of PDAC by converting latent TGF-β1 complexes to their active form through loss of the tumor suppressor Smad4 and upregulation of MMP-9 production." (PMID 40507347, 2025).
tumor (continued). "For instance, selective MMP-9 inhibitors have shown potential in limiting tumor invasiveness and enhancing therapeutic sensitivity, while MMP-14 (MT1-MMP)-specific inhibitors have effectively restricted tumor invasion and improved the response to radiation therapy." (PMID 40265458, 2025). "By targeting tumour cells through HER2 and releasing the MMP2/MMP9 inhibitor at specific sites within the tumour microenvironment, we could achieve reduced adverse events and enhanced therapeutic impact." (PMID 40259907, 2025). "Therefore, targeting MMP-9 is crucial for research on anti-tumor angiogenesis, invasion, and metastasis." (PMID 40284474, 2025). "Tumor AOPPs were significantly correlated with tumor MMP-9 expression (p < 0.0001, r = 0.63)." (PMID 40729026, 2025). "Additionally, MMP‐9 can enhance the invasive and metastatic capabilities of tumor cells by degrading and remodeling the extracellular matrix and releasing vascular endothelial growth factors." (PMID 40808216, 2025). "Similarly, self-delivery nanoparticles containing low-molecular-weight heparin prevented lung PMN formation by blocking P-selectin/PSGL-1-mediated MDSC recruitment and also suppressed MMP-9 expression, thereby inhibiting circulating tumor cell colonization." (PMID 41463352, 2025). "Neutrophil-derived MMP-9 has been shown to contribute to cancirogenesis by degrading extracellular matrix components, facilitating tumor invasion, and accelerating angiogenesis through the release of matrix-bound pro-angiogenic factors such as vascular endothelial growth factor (VEGF)." (PMID 40920704, 2025). "NETs remodel ECM via NE and MMP-9, awaken dormant tumor cells, and trap CTCs." (PMID 40805288, 2025). "Consistent with previous studies 88, we observed significant upregulation of FAPα and matrix metalloproteinase 9 (MMP9) across the majority of cancer types analyzed, highlighting their relevance in tumour biology, as they have been associated to tumour progression and/or metastasis." (PMID 40083695, 2025). "In addition, MMP9 secreted by these neutrophils further enhances tumor neoangiogenesis, thereby promoting the development of pancreatic and lung cancers." (PMID 40564191, 2025). "Furthermore, the tumor cells from regions with a rich presence of adjacent α‐SMA‐expressing stromal cells revealed an upregulation of matrix metalloproteinase‐9 (MMP9) expression in grade 3 tumors." (PMID 39245631, 2025). "Furthermore, VEGF promotes organ-specific MMP-9 expression, and its inhibition lowers MMP-9 levels, preventing ascites and reducing intraperitoneal tumor load." (PMID 40369674, 2025). "Immunohistochemical staining revealed that the expression of FOXM1, Ki67, and MMP9 in the tumor tissues of mice inoculated with Huh7 cells co-cultured with exosomes from hypoxia-induced HepG2 cells significantly increased (p = 0.005, p < 0.001, p = 0.003) when compared to that in the control group." (PMID 40486884, 2025). "MMPs, specifically MMP-2 and MMP-9, facilitate angiogenesis, tumor growth, and cancer spread." (PMID 41179937, 2025). "Furthermore, levels of circular RNAs (circRNAs) such as circRNA DOCK1, produced through exon circularization, are elevated in tumor cells and facilitate the accumulation of MMP-9 in cancers." (PMID 40565017, 2025). "Inhibition of the immune system and the expression of MMP-9 and VEGF-A, which stops cancer from growing, in addition to suppression of the expression of c-Met, ki-67, and MMP-9 that results in inhibition of tumour cells invasiveness and proliferation and induction of apoptosis." (PMID 40427522, 2025). "While MMP9 may be more reflective of systemic processes, GNL expression appears to be closely associated with tumour-specific glycosylation patterns, which warrants future investigations." (PMID 41041068, 2025).
tumor (continued). "Recent studies have highlighted the significance of the reactive oxygen species (ROS)–nuclear factor kappa B (NF-κB)–matrix metalloproteinase-9 (MMP-9) axis in promoting tumor invasion and metastasis in CRC, linking oxidative stress with inflammatory signaling and extracellular matrix degradation." (PMID 40729026, 2025). "Suppressing MMP9 using specific inhibitors, such as small-molecule compounds or monoclonal antibodies, could reduce tumor progression and improve treatment efficacy." (PMID 40299352, 2025). "Furthermore, we examined the expression of MMP2/MMP9 in in vivo experiments, which showed that the expression levels of MMP2/MMP9 proteins in the tumor of the shRNA-HIF-1α group were decreased compared to the shRNA-NC group." (PMID 39781344, 2025). "MMP-2 and MMP-9 degrade type IV collagen, increasing the availability of angiogenic factors, and promoting tumor angiogenesis, which provides nutrients and oxygen to tumor cells." (PMID 39911388, 2025). "Meanwhile, in the tumour microenvironment, invasion may be inhibited by down-regulating pro-metastatic MMPs (e.g. MMP-9)." (PMID 40495147, 2025). "The overexpression of MMP9 plays a critical role in the invasion and metastasis of tumor cells." (PMID 41305721, 2025). "Additionally, high CD20 was significantly linked with MMP-9 expression, a critical enzyme involved in ECM remodeling and tumor progression." (PMID 40821783, 2025). "Thus, research has increasingly focused on designing selective inhibitors that target specific MMPs associated with tumor progression, notably MMP-2, MMP-9, and MMP-14." (PMID 40265458, 2025). "In addition, MMP‐9 promotes tumor growth and angiogenesis through the release of VEGF‐A and the suppression of antiangiogenic factors." (PMID 41049266, 2025). "MMP-9 is considered crucial for the metastatic ability of tumor cells." (PMID 40298802, 2025). "In addition, GOS inhibits TNF-induced MMP9 expression: Tumor necrosis factor (TNF) can stimulate the production of matrix metalloproteinase 9 (MMP9), an enzyme that degrades the extracellular matrix and facilitates tumor invasion and metastasis." (PMID 40002373, 2025). "Furthermore, some studies in cancer models suggest that N2 TANs are more prone to NETosis and that, reciprocally, NETosis skews neutrophils in the tumor microenvironment to an N2 phenotype, possibly by MMP9 activation of latent TGFb in the NET." (PMID 40523023, 2025). "Moreover, studies using conditioned medium from TAMs and TAM/cancer cell line co-cultures have shown that TAMs promote cell migration and invasion of various human tumour cell lines via an MMP9-dependent mechanism." (PMID 40385641, 2025). "In addition, GBM-secreted sEVs contain the matrix metalloproteinases (MMPs) MMP-2 and MMP-9 in their crown, which promote extensive hydrolysis of the extracellular matrix and increase tumor aggressiveness." (PMID 39996852, 2025). "F.n may drive tumor growth and metastasis by suppressing T-cell infiltration and upregulating matrix metalloproteinase-9 (MMP-9)." (PMID 40792109, 2025). "Studies suggest that increased MMP-9 expression may enhance the migratory and invasive capabilities of various tumor cell types." (PMID 40570009, 2025). "This suggests that MMP-2 may play a distinct and possibly less critical role in SP-mediated tumor biology compared to MMP-9." (PMID 40321254, 2025). "Nevertheless, the observed increase in MMP-2 and MMP-9 expression in CAR-T cells may contribute to their migration from the tumor vasculature, highlighting their additional therapeutic role." (PMID 40666525, 2025). "In cancer, MMP9 released by neutrophils can promote tumour angiogenesis." (PMID 39847394, 2025). "This may indicate that high sera MMP-9 levels might non-invasively reflect tumor activity and serve as a biomarker of aggressiveness." (PMID 41573658, 2025).
tumor (continued). "This review highlights the mechanistic roles of salivary biomolecules, including microRNAs (miRNAs) (e.g., miR-31, miR-200a), proteins (interleukin-8 (IL-8), matrix metalloproteinase-9 (MMP-9)), circulating tumor DNA (ctDNA), and metabolites, in OSCC pathogenesis." (PMID 41450375, 2025). "Decreased miR-138 expression also increases MMP-2 and MMP-9, promoting tumor metastasis." (PMID 41356146, 2025). "Within the tumor microenvironment, MMP-9-dependent release of matrix-bound growth factors amplifies proangiogenic signaling, activates stromal fibroblasts, and drives epithelial–mesenchymal transition (EMT), thereby promoting neovascularization, invasive growth, and metastatic dissemination." (PMID 41304763, 2025). "Moreover, antisense RNA-mediated suppression of MMP-9 markedly decreases tumor vascular density in nude mouse models, highlighting MMP-9 as a promising therapeutic target." (PMID 40630800, 2025). "In addition, primary tumor-derived signals upregulate MMP9 and MMP2 in hepatic sinusoidal lining cells." (PMID 41463352, 2025). "Additionally, HDAC1, HDAC6, and HDAC8 contribute to tumor invasion by increasing matrix metalloproteinase-9 (MMP-9) expression." (PMID 40091020, 2025). "Molecular docking simulations were performed to analyze the binding affinities of these agents to MMP2 and MMP9, alongside scratch assays and gene expression analysis to assess their inhibitory effects on these key enzymes involved in tumor invasion and cell migration." (PMID 40136519, 2025). "It is well documented that MMP9 is a critical factor in promoting tumor metastasis in PCa." (PMID 41562091, 2025). "Neutrophil elastase and MMP9 in the extracellular DNA sequentially cleave the extracellular protein laminin, revealing an epitope that triggers the proliferation of dormant metastatic tumor cells in the lungs of mice." (PMID 39653768, 2025). "Additionally, MMP-2 and MMP-9 facilitate tumor invasion and angiogenesis through the proteolytic activation of TGF-β." (PMID 41153831, 2025). "Additionally, ROS-induced NF-κB, HIF-1α, and TGF-β pathways increased uPA and MMP-9 for extracellular matrix reshaping, affecting the integrity of intercellular connections in tumor cells and activating the PI3K/AKT pathway to promote tumor cell mobility." (PMID 40847302, 2025). "Our data propose that SP-driven MMP-9 activity may be instrumental in promoting brain metastases through enhanced tumor invasiveness and ECM degradation." (PMID 40321254, 2025). "MMP-9-targeted therapies can synergistically enhance anti-tumor efficacy as well." (PMID 40284474, 2025). "The remodeling of the ECM by MMP-2 and MMP-9 can also modulate the local immune response, potentially aiding the tumor in evading immune surveillance and changes in the ECM can influence the infiltration and activity of immune cells in the tumor microenvironment." (PMID 39858430, 2024). "A previous study showed that HMGB1 could bind to RAGE, activate the MAPK signaling pathway, and then cause the activation of matrix proteases MMP9 and MMP2, degraded extracellular matrix, and promote tumor invasion and metastasis." (PMID 38577597, 2024). "Furthermore, Echinacoside has been found to suppress the expression of MMP9 and fascin, two proteins that play a critical role in tumor invasion and metastasis, while increasing the expression of E-Cadherin." (PMID 38461536, 2024). "The MMP-9 gene promotes tumor invasion, metastasis, and angiogenesis in cancer cells." (PMID 38481883, 2024). "Furthermore, the tumor invasion-related proteins MMP-7 and MMP-9 were decreased in the context of MMP-12 deficiency." (PMID 38511770, 2024). "MMP2 and MMP9 are often overexpressed in cancers and promote tumor metastasis." (PMID 38430256, 2024).